IGF2BP3 (insulin like growth factor 2 mRNA binding protein 3)
Diseases named in the same sentence as IGF2BP3 in open-access papers (continued):
Sharing a sentence is not in itself a finding about the gene and the disease.
lung carcinoma (31 papers, 2015 to 2026). "Kaplan-Meier curves revealed that lung cancer patients with higher IGF2BP3 expression levels were associated with poor overall survival, suggesting that increased IGF2BP3 levels contribute to lung cancer progression." (PMID 40770637, 2025). "Previously, our group demonstrated that IGF2BP3 is a tumor antigen of diagnostic value for lung cancer." (PMID 29212181, 2017). "High and strong expression of IGF2BP3 is associated with moderately/poorly differentiated lung cancer and predicts poor prognosis." (PMID 29212181, 2017). "Currently, some studies have demonstrated the association among HOXA10, IGF2BP3, and lung cancer." (PMID 33614509, 2020). "Data currently available by us and others suggest that IGF2BP3 in lung cancer may be of diagnostic or prognostic values." (PMID 29212181, 2017). "Previously, our group reported that IGF2BP3 may serve as a potential diagnostic marker for lung cancer." (PMID 29212181, 2017). "This notion was supported by a previous single immunohistochemical study, in which it was reported that IGF2BP3 may be a potential diagnostic marker for high grade of lung cancers." (PMID 29212181, 2017). "Therefore, both autoantibodies against IGF2BP3 in lung cancer patients and the high expression of IGF2BP3 in lung cancer tissues may be of diagnostic value for lung cancer." (PMID 29212181, 2017). "Researches have examined the m6A writer VIRMA and the reader IGF2BP3 in relation to the progression of several types of cancer, including liver, breast, and lung cancers." (PMID 41513610, 2026). "To further verify our assumption, we determined the IGF2BP3 level in clinical lung cancer tumors by IHC staining." (PMID 40770637, 2025). "RIG represses IGF2BP3 expression and sensitizes lung cancer ​cells to RSL3 and erastin-induced ferroptosis, suggesting that RIG can inhibit tumor growth and promote programmed cell death." (PMID 37554271, 2023). "This suggests that peptides derived from IGF2BP3 are attractive targets for lung cancer immunotherapy." (PMID 37298373, 2023). "In lung cancer, circ_MMP2 (also known as circ_0039411) can bind to insulin-like growth factor 2 mRNA binding protein 3 (IGF2BP3), thus expediting cell proliferation and EMT by stabilizing FOXM1 transcripts." (PMID 35055115, 2022). "The immunogenicity of IGF2BP3 has been confirmed by the existence of antibodies against recombinant IGF2BP3 protein in the pleural effusions from patients with lung cancer." (PMID 35593226, 2022). "We also found the alternative splicing pattern of the PKM gene, a kinase of pyruvate and its splicing pattern highly expressed in lung cancer cells, which is regulated by IGF2BP3." (PMID 32984260, 2020). "Previous study has reported that the expression IGF2BP3 or IGF2BP1 can predict poor overall survival in lung cancer patients, which were consistent with our results." (PMID 32071816, 2020). "Then, we found that IGF2BP3 is highly expressed in lung cancer tissues and low in normal lung tissues." (PMID 32984260, 2020). "In agreement with the subcutaneous lung cancer model, IGF2BP3 overexpressing group in the metastatic lung cancer model also showed reduced survival rate." (PMID 29212181, 2017). "We first analyzed IGF2BP3 DNA copy numbers in lung cancer tissues by two DNA datasets in the Oncomine database." (PMID 29212181, 2017). "To further confirm the high expression of IGF2BP3 in lung cancer tissues, we performed Real-time PCR and immunohistochemical analysis to assess the expression of IGF2BP3 in lung cancer at both mRNA and protein levels." (PMID 29212181, 2017).
lung carcinoma (continued). "Kaplan-Meier database suggests that lung cancer patients with high IGF2BP3 has relatively short survival time." (PMID 29212181, 2017). "Elevated IGF2BP3 DNA copy numbers were observed in lung adenocarcinoma, squamous cell lung carcinoma, and mixed types of lung cancer compared to normal lung tissues in TCGA lung dataset and Weiss lung dataset." (PMID 29212181, 2017). "Among lung cancer cell lines detected, highest expression of IGF2BP3 protein was observed in A549 cells and the lowest expression was observed in H460 cells." (PMID 29212181, 2017). "When the transwell membrane was coated with matrigel, IGF2BP3 overexpressing lung cancer cells showed increased ability to migrate through the membrane." (PMID 29212181, 2017). "Here we demonstrate that IGF2BP3 expression was markedly increased in lung cancer tissues compared to normal tissues at both mRNA and protein levels." (PMID 29212181, 2017). "Compared to control cells, the injection of IGF2BP3 overexpressing lung cancer cells led to a significantly increase in tumor volume." (PMID 29212181, 2017). "In the present study, we systematically explored the participation of IGF2BP3 in lung cancer development." (PMID 29212181, 2017). "Overexpression of IGF2BP3 in lung cancer cells promoted cell proliferation, tumor migration and invasion in vitro and in vivo, whereas knockdown of IGF2BP3 exhibited opposite effects." (PMID 29212181, 2017). "In our previous study, autoantibodies against IGF2BP3 were observed in a few fractions of patients with IGF2BP3-positive lung cancer." (PMID 29212181, 2017). "Transwell assays showed that overexpression of IGF2BP3 in H460 cells led to a significant enhanced lung cancer cell migration compared to mock control." (PMID 29212181, 2017). "Experimentally, we indeed observed that IGF2BP3 was highly expressed in lung cancer tissues both at mRNA and protein level." (PMID 29212181, 2017). "We next examined IGF2BP3 protein expression in a tissue array containing 10 normal and 70 lung cancer tissues." (PMID 29212181, 2017). "In addition, both RNA and protein levels of IGF2BP3 in lung cancer samples were higher than those in normal samples, as shown by data obtained from TCGA." (PMID 40770637, 2025). "In lung cancer, IGF2BP3 has been reported to have the ability to regulate the alternative splicing of Pyruvate kinase M (PKM), suggesting that IGF2BP3 may play a role in regulating glucose metabolism reprogramming." (PMID 38565547, 2024). "In conclusion, IGF2BP3 plays a tumor-promoting role in lung cancer, may be related to immunotherapy, and is involved in constructing many prognostic models." (PMID 37298373, 2023). "Moreover, the activated circITGB6/IGF2BP3/PDPN axis is closely correlated to metastasis status in lung cancer patients, increased lymph node metastasis as well as worse prognosis in CRC patients, reinforcing the critical role of circITGB6 in tumor metastasis." (PMID 37898647, 2023). "Similarly, IGF2BP3 affects 121 alternative splicing events involving cassette exon, 5pMXE and 3pMXE, with 61 specific alternative splicing genes in lung cancer." (PMID 37850412, 2023). "IGF2BP3 is also involved in constructing different predictive models of lung cancer." (PMID 37298373, 2023). "Aggregating our results, our observation might offer a new evidence about the mechanisms of how IGF2BP3 having an impact on lung cancer." (PMID 32984260, 2020). "Here we further explored the impact of IGF2BP3 on lung cancer migration and invasion." (PMID 29212181, 2017). "Here, we uncovered an unknown function of IGF2BP3 to be as a posttranslational modulator in lung cancer development." (PMID 29212181, 2017).
lung carcinoma (continued). "The increased protein expression of IGF2BP3 in lung cancer was also documented." (PMID 29212181, 2017). "To elucidate whether IGF2BP3 involved in these processes, we monitored changes in cell behavior following upregulation of its expression in lung cancer cell lines." (PMID 29212181, 2017). "Furthermore, overexpression of IGF2BP3 promoted the tumorigenesis of lung cancer cells and lung metastasis in vivo, leading to decreased survival rate." (PMID 29212181, 2017). "Notably, our data demonstrated that IGF2BP3 is prone to be expressed in high grade of lung cancer tissues." (PMID 29212181, 2017). "In contrast, positive expression of IGF2BP3 was observed in 32 (45.7%) lung cancer tissues." (PMID 29212181, 2017). "Besides, IGF2BP3 was highly expressed in a variety of cancer cell lines including lung cancer cell lines." (PMID 29212181, 2017). "Therefore, drugs that modulate the expression of IGF2BP3 may be a strategy to inhibit the progression of lung cancer." (PMID 37298373, 2023). "Of note, a recent study showed IGF2BP3 may regulate alternative splicing of PKM in lung cancer." (PMID 34321607, 2022). "Our data extend the knowledge that IGF2BP3 may also be a prognostic marker in lung cancer." (PMID 29212181, 2017). "Notably, IGF2BP3 is prone to be expressed in high grade of lung cancer (P = 0.047)." (PMID 29212181, 2017). "However, little is known about the function of IGF2BP3 in lung cancer development." (PMID 29212181, 2017). "Lung cancer patients with high expression of IGF2BP3 had shorter survival rate compared to those with low expression of IGF2BP3.Thus, both in vitro and in vivo assays suggest that overexpression of IGF2BP3 promotes proliferation, metastasis and tumorigenicity of lung cancer cells." (PMID 29212181, 2017). "The results showed that IGF2BP3 positively regulated PDPN mRNA and protein levels in lung cancer cells." (PMID 37898647, 2023). "The results further validated the importance of competitive relationships among HOXA11-AS, IGF2BP3, and HOXA10 in lung cancer progression." (PMID 33614509, 2020). "Specifically, IGF2BP3 regulates the alternative splicing patterns of PKM genes, known for aberrant splicing in various cancers, potentially promoting lung tumourigenesis and offering a novel therapeutic target for patients with lung cancer." (PMID 37850412, 2023). "Lung cancer also has high expression profile of GCNT3 (a gene regulating mucin synthesis), GOLM1(a gene coding for a Golgi transmembrane protein) and IGF2BP3 (a gene coding for a RNA binding protein), which are all positively correlated with malignant progression of lung cancer." (PMID 33129284, 2020). "In fifteen paired lung cancer and non-cancerous lung tissues, IGF2BP3 mRNA expression was upregulated in 6 out of 8 adenocarcinoma and 6 out of 7 squamous cell carcinoma tissues as compared to adjacent non-cancerous tissues." (PMID 29212181, 2017). "By contrast, insulin-like growth factor 2 mRNA binding protein 3 (IGF2BP3) was also identified as a promising CPA in our screen, showing relatively high prevalence of expression in ~15 different cancer types, including glioblastoma, uterine, testicular, and lung cancers." (PMID 33087697, 2020).
lung carcinoma (continued). "Previously, studies have investigated the role of thirteen m6A regulatory genes in lung cancer, but the roles of seven newly discovered ones, namely, METTL16, YTHDF3, IGF2BP1, IGF2BP2, IGF2BP3, HNRNPG, and HNRNPA2B1 has not been determined." (PMID 33795529, 2021).
bladder cancer (30 papers, 2020 to 2026). "The differential genes obtained from TCGA-BLCA and GSE166716 datasets along with the identified risk factors for bladder cancer were included in this diagram for mapping purposes and showed IGF2BP3 was the only intersection gene." (PMID 40083693, 2025). "The m6A binding and stabilization of CDK6 by IGF2BP3 represents a potential molecular mechanism underlying cisplatin resistance in bladder cancer cells." (PMID 40083693, 2025). "We performed RNA-seq sequencing analysis and identified cell cycle pathway which enriched and associated with IGF2BP3 in bladder cancer." (PMID 40083693, 2025). "KEGG pathway analysis elucidated cell cycle pathway was enriched and associated with IGF2BP3 in bladder cancer." (PMID 40083693, 2025). "In this study, we demonstrated that elevated expression of IGF2BP3 was associated with poor prognosis of bladder cancer patients." (PMID 40083693, 2025). "Subsequently, through univariate Cox regression analysis, we identified ALKBH5, FTO, IGF2BP2, and IGF2BP3 as potential risk factors for bladder cancer." (PMID 40083693, 2025). "As a result, we were prompted to explore the possible functions and underlying mechanisms of IGF2BP3 in the advancement of bladder cancer." (PMID 38504159, 2024). "Of note, IGF2BP3 was the only gene that is not only overexpressed in bladder cancer, but also its elevated expression was linked to unfavorable overall survival of BLCA patients." (PMID 38504159, 2024). "Analysis from GSE19423, a Bacillus Calmette–Guérin (BCG) immunotherapy of bladder cancer dataset, also revealed that a high level of IGF2BP3 was associated with favorable overall survival and cancer-specific survival in patients with bladder cancer." (PMID 38504159, 2024). "We next explored the underlying molecular mechanisms of IGF2BP3 in the advancement of bladder cancer." (PMID 38504159, 2024). "To examine the potential oncogenic function of IGF2BP3 in the development of bladder cancer, we conducted overexpression and loss-of-function studies." (PMID 38504159, 2024). "Collectively, our results suggest that IGF2BP3 is upregulated in bladder carcinoma, and its elevated expression is linked to unfavorable clinicopathological characteristics, implying its possible oncogenic function in bladder cancer." (PMID 38504159, 2024). "Regardless, IGF2BP3 is highly expressed in bladder cancer patients and independently associated with bladder cancer recurrence, cancer-specific mortality, and all-cause mortality." (PMID 36831493, 2023). "Univariate logistic regression analysis was performed to further assess the association between IGF2BP3 expression and clinicopathological features of bladder cancer." (PMID 36732736, 2023). "To further investigate the mechanisms underlying the regulatory function of IGF2BP3 in the proliferation of bladder cancer cells, we performed flow cytometry assays with Annexin V and PI double staining in UMUC3, T24, 5637 and J82 cell lines." (PMID 33094561, 2020). "To investigate the potential mechanism underlying the role of IGF2BP3 in bladder cancer proliferation and chemotherapy resistance, we initially conducted RNA-seq analysis on T24 cells with IGF2BP3 knockdown and control groups, each consisting of three biological replicates." (PMID 40083693, 2025). "In addition, the association between elevated IGF2BP3 levels and unfavorable survival was validated in six additional bladder cancer datasets." (PMID 38504159, 2024). "Moreover, elevated levels of IGF2BP3 are linked to enhanced proliferation, invasion, and unfavorable prognosis among individuals with bladder cancer." (PMID 38504159, 2024). "Given that these cells, especially the CD8 + T cells, play important roles in immunotherapy, we investigated whether IGF2BP3 level was associated with immunotherapy efficacy in bladder cancer." (PMID 38504159, 2024). "Moreover, we investigated the association between mRNA expression of IGF2BP3 and overall survival in bladder cancer patients." (PMID 36732736, 2023).